PRL (prolactin)
Diseases named in the same sentence as PRL in open-access papers (continued):
Sharing a sentence is not in itself a finding about the gene and the disease.
tumor (continued). "The decrease in serum IGF-1 levels during combined therapy was not correlated with basal GH, IGF-1, and PRL levels, the tumor size before cabergoline add-on therapy." (PMID 35612842, 2022). "PRL does not reliably reflect an increase in tumor size and thus is not useful for clinical assessment." (PMID 35000899, 2022). "In responsive patients, Cab achieves progressive PRL decrease and tumor shrinkage for years, reaching hormone normalization and tumor shrinkage up to its disappearance or empty sella in most." (PMID 35000899, 2022). "From a practical point of view, Cab treatment should not be withdrawn if PRL levels reincrease after lowering Cab dose, and the management should be different according to sex and tumor size." (PMID 35000899, 2022). "After four months, no decrease in PRL level nor tumor size was achieved, so transsphenoidal surgery was performed as the next step." (PMID 35865778, 2022). "Another exciting aspect is that although cabergoline restores circulating PRL levels in PRLRKO mice, it does not induce tumor reduction, suggesting that dopamine and PRL effects can be interplaying but also have separate actions." (PMID 36714572, 2022). "We followed the other two patients for invasive macroadenomas larger than 4 cm on cabergoline at a maximum dose of 4.5 mg/week without normalization of PRL or regression of tumor size on MRI." (PMID 36540468, 2022). "Although the decrease in IGF-1 levels was not correlated with a reduction in PRL level and tumor size, in the controlled group, the tumor size was found to be larger than the other group." (PMID 35612842, 2022). "PRRT was used in 11 patients (5 not previously reported), predominantly in PRL-secreting and NF tumours." (PMID 36018781, 2022). "Dopamine receptor type 2 (DRD2) mediates a reduction of p-AKT in a subgroup of non-functioning PitNETs (NF-PitNETs) and in prolactin-secreting tumor cells (MMQ cells) through a β-arrestin 2-dependent mechanism." (PMID 35721701, 2022). "In most cases the tumor secretes only gonadotropins (either one, most frequently FSH, or both), but co-secretion of other pituitary hormones, namely Thyroid Stimulating Hormone (TSH), Prolactin (PRL), and Adrenocorticotropic Hormone (ACTH), was reported." (PMID 36013538, 2022). "Consistent with the poor efficacy of bromocriptine treatment, the PRL levels of the patients did not return to normal with endocrinological symptoms, and some patients still showed symptoms of tumor mass compression." (PMID 35741585, 2022). "Except for a few studies, the specific effects of PRL levels and tumor sizes have not been described." (PMID 35741681, 2022). "But most studies defined resistance to DA as a lack of PRL normalization and a failure to decrease tumor size despite an adequate dose of DA treatment for 3 or 6 months." (PMID 35395837, 2022). "Elevated PRL levels derived from prolactinomas are not part of a response to a metabolic challenge, they result from a diseased state (tumor) and are not considered HomeoFIT-PRL (and are usually above 100 μg/L)." (PMID 36213259, 2022). "The patients took bromocriptine for 3 months, but their serum prolactin did not return to normal levels, and the tumour volume was reduced by less than 50%." (PMID 34814904, 2021). "Our large series of cases with AIP variants identified 10% of patients with prolactinomas, while tumours with negative GH and prolactin staining are exceedingly rare." (PMID 33010004, 2021). "Patients with high prolactin levels (above 3 times the upper limit of the normal value) with a high probability of a mixed GH-prolactin secreting tumor, were not included in the analysis." (PMID 35211089, 2021). "During the 6-month follow-up period, the tumor did not relapse again, and the PRL level was also normal." (PMID 33776913, 2021). "The T2 SI ratio, prolactin index, tumor volume, and maximal diameter were not significantly different between patients with CSF rhinorrhea and non-responders." (PMID 34771538, 2021).
tumor (continued). "The tumor volume, prolactin index, and maximal tumor diameter showed no significance between the two groups." (PMID 34771538, 2021). "All this orchestrated process explains in part why in general, but not invariably, prolactin secretion and tumour volume are in parallel in prolactinomas." (PMID 34681905, 2021). "It is fair statement that the precise role of PRL and its receptor in tumor biology is not yet clear but the present results taken together with previous investigations support a role for PRL/PRLR as being an onco-modulatory factor." (PMID 34358244, 2021). "Baseline characteristics such as plasma prolactin (PRL) levels, tumour size or radiological features such as invasion, are not prognostic factors of aggressiveness per se." (PMID 34681905, 2021). "A microarray analysis performed with MCF7 BC cells showed that the binding of PRL with PRLR could induce the 1.2-fold upregulation of approximately 4,700 genes, which are involved in the activation of pathways related to neoplasm proliferation and progression." (PMID 34745013, 2021). "After 12 months of CAB treatment (up to 4.5 mg/week), PRL levels were reduced, without a significant shrinkage of the tumor." (PMID 34173929, 2021). "This option can lead to better control of PRL levels and to the shrinkage of tumor size, without serious adverse events." (PMID 34173929, 2021). "A dopamine agonist normalizes serum prolactin (PRL) and shrinks tumor volume, but 10–30% of cases do not undergo remission with the maximum tolerated dose; these cases are known as dopamine agonist-resistant prolactinomas." (PMID 34925244, 2021). "Prolactin microadenomas with clinical symptoms generally do not develop into macroadenomas, and some prolactinomas are aggressive, with enlarged tumours and elevated blood prolactin levels." (PMID 34814904, 2021). "Univariable analysis revealed that male sex, high preoperative PRL levels, Knosp grading (i.e., Knosp grade 1), and tumor size (i.e., macroadenoma) were related to early negative surgical results (i.e., PRL levels > 20 μg/L)." (PMID 33847973, 2021). "Seven months after GKS treatment, MRI revealed that the tumor size was slightly decreased, and the serum prolactin level was reduced from 200.0 ng/mL (samples not diluted) to 57 ng/mL." (PMID 34715828, 2021). "Activation of these pathways is a well-known phenomenon in HCMV-infected cells and HCMV-induced function of the PRL/PRLR axis may therefore result in increased cellular proliferation and tumor progression via binding to the highly abundant PRLR in tumors." (PMID 32121009, 2020). "Symptom duration before surgery was associated with age (r = 0.495, p < 0.001), but it was not related to preoperative prolactin concentrations (r = 0.275, p = 0.059) or to maximum tumor diameter (r = 0.212, p = 0.149)." (PMID 32733387, 2020). "PRL+ cells were readily detected in tumour cells within the tumour mass as well as in those infiltrating the non-neoplastic brain parenchyma." (PMID 31862900, 2019). "Although circulating PRL may play a role in the pathogenesis of GBM, expression of PRL and PRLR in the tumour microenvironment may exert autocrine/paracrine effects that modulate GBM cell behaviour." (PMID 31862900, 2019). "One patient was treated with dopamine agonist, resulting in a normalization of prolactin levels, but without change in tumor size." (PMID 31766255, 2019). "Throughout treatment, the tumor was resistant to this dopamine agonist; the prolactin levels never normalized, and the tumor did show cystic degeneration but never disappeared." (PMID 31202268, 2019). "While in the general population tumour PRL/PRLR expression did not correlate with patient survival, biological sex-stratified analyses revealed that male patients with PRL+/PRLRHIGH GBM performed worse than PRL+/PRLRLOW GBM." (PMID 31862900, 2019).
tumor (continued). "Considering the role of growth hormone and prolactin in regulation of SOCS genes expression, any change in the secretion of these hormones in the tumor microenvironment might also alter SOCS expression." (PMID 30453988, 2018). "Prolactin concentrations were not normalized, despite significant decreases, and the reduction in tumor size was <50% according to the imaging assessments performed at the initial stages of the treatment." (PMID 30542321, 2018). "Pre-operative trials of a dopamine agonists (bromocriptine or carbergoline) in three of these patients had no influence upon on tumour size or prolactin levels." (PMID 29363000, 2018). "On pathological examination, the tumor was negative for prolactin (PRL), growth hormone (GH), adrenocorticotrophic hormone (ACTH), follicle-stimulating hormone (FSH), luteinizing hormone (LH), and thyroid-stimulating hormone (TSH)." (PMID 29587659, 2018). "Finally, in the residual tumour of a TNBC cell line-based MDA-MB-231-derived tumour following si-hVDAC1 treatment, increased levels of prolactin, estrogen and progesterone receptors, as well as Her2, were noted." (PMID 30544833, 2018). "The SOX2+ cell progeny (as indicated by “yellow fluorescent protein” or YFP+ signal) increased in abundance during tumor development and growth, but co-localization of YFP and PRL was low, indicating that the large majority of the tumor (PRL+) cells did not descend from the SOX2+ (stem) cells." (PMID 29255445, 2017). "In contrast, the stiffness of the extracellular matrix, not the concentration of collagen-I ligand, controls PRL signals to the pro-tumor progressive FAK/SFK/ERK1/2 signaling cascade." (PMID 27344177, 2016). "Plurihormonal hyperactivity may be diagnosed in a patient with MPA when more than one tumor is clinically active (e.g., ACTH and PRL) or in cases with at least one composite tumor (e.g., GH and PRL), to complicate the clinical scenario." (PMID 26869991, 2016). "Several studies have demonstrated that lack of response after three cycles, either in tumor size or prolactin levels, is predictive of a poor outcome." (PMID 27489751, 2016). "Additionally, a recent study showed the utility of prolactin in improving tumor location by using the ratio of the interpetrosal gradient of ACTH and the interpetrosal gradient of prolactin." (PMID 27355856, 2016). "The lack of tumor growth and/or dissemination in the PRL treated group was also confirmed by histological examination of lung and liver tissues." (PMID 27480353, 2016). "In our patients, we observed that pre-treatment PRL levels did not correlate with the tumor size evolution in the menopause." (PMID 26909481, 2016). "Together, in our study, 56% of the patients (14/25) received low-dose BRC treatments without relapse of tumor volume or PRL level." (PMID 27999593, 2016). "Just like in microprolactinomas, it is not necessary to measure serum prolactin levels throughout pregnancy, because levels do not uniformly increase during gestation and do not correlate with tumor enlargement." (PMID 26074878, 2015). "Although there are no immunocytochemical results for tumor #4, the patient exhibited an excessive secretion of both GH and PRL." (PMID 26106585, 2015). "Surgery is a second line option for the treatment of giant prolactinomas, as it confers morbidity risks and usually fails to normalize PRL or to remove the entire tumor." (PMID 28702224, 2015). "Whereas tumors #2 and #3 contained mostly GH cells and much less frequently PRL, tumor #1 cells stored no hormone, although a minor fraction of cells stored FSH, PRL, and GH." (PMID 26106585, 2015). "Patients with lower PRL levels and no visible tumor on MRI seemed to be the most likely to benefit from this approach but it was also effective in subjects with small tumor remnants." (PMID 25699020, 2015). "Prolactin tends to increase during pregnancy; therefore, it does not reliably reflect an increase in tumor size and is not useful for clinical assessment." (PMID 26074878, 2015).
tumor (continued). "Immunohistochemically, the tumor cells were positive for prolactin, chromogranin-A, and synaptophysin, but were negative for glial fibrillary acidic protein, S-100 protein, epithelial membrane antigen, and vimentin." (PMID 26228535, 2015). "Consistent with a D2-action, WEFHG did not affect PRL in rat pituitary lactotropic tumor-derived GH3 cells that lack the D2 receptor expression." (PMID 25254056, 2014). "Sequential head magnetic resonance imaging revealed no tumor shrinkage in all of them despite serum prolactin concentration was decreased." (PMID 25142896, 2014). "Consistent with a D2-action, WEFHG did not affect PRL in rat pituitary lactotropic tumor-derived GH3 cells that lack the D2 receptor expression but significantly increased the expression of D2 receptors and DAT in PC12 cells." (PMID 25254056, 2014). "After a further 12 months of treatment, prolactin level was reduced to 22 ng/ml (normal range: 3–17 ng/ml), but did not normalize; however tumor remained stable." (PMID 25165538, 2014). "The FSH, LH, P and PRL levels did not change significantly in tumor stage groups I–IV compared with stage 0." (PMID 24137476, 2013). "Since cellular proliferation and blood vessel formation are indispensable for the tumor development, our study may suggest the participation of RAS in pathogenesis of estrogen-induced PRL-secreting adenoma." (PMID 22645419, 2012). "Withdrawal of cabergoline was considered if patients had normal prolactin levels and either no tumor visible by MRI or at least 50% reduction in tumor volume." (PMID 20478050, 2010). "No other significant differences in PRL levels were noted across the tumour characteristics of tumour grade, size, node involvement, and ER, PR, or HER2 expression." (PMID 20736944, 2010). "Experimental studies proposed that PRL could act as a local growth factor and may stimulate the proliferation of mammary NMU-induced tumours." (PMID 18045456, 2007). "The aim of the study was to assess the effect of metoclopramide on tumour development of NMU-induced tumours in Wistar rats, and at the same time to study acute and chronic administration of (LH-RH analogue) goserelin on PRL, TNFα and NO expression in this experimental model." (PMID 18045456, 2007). "We conclude that PTTG does not correlate with prolactin levels or tumor size in animal models prolactinoma, and its pituitary content is not related to a decrease in dopaminergic control of the lactotrope, but to estrogen action at the pituitary level." (PMID 17222350, 2007). "It was higher basal PRL plasma levels in rats with NMU induced tumours than in basal controls without tumour (p < 0.001)." (PMID 18045456, 2007). "This suggests that the pituitary hormonal deficiencies of the dwarfs (growth hormone, thyroid stimulating hormone and prolactin) did not influence the tumour induction nor the development of the different tissues present in this type of tumour." (PMID 6534385, 1984). "Perphenazine (Pz) produced a dose-related increase in plasma PRL, but stimulation of tumour growth in the absence of E2 required a minimal level of plasma PRL induced by Pz (0.15 mg/100 g body wt/day or more)." (PMID 6788061, 1981). "From these findings it is postulated that the mechanism of action whereby P maintains static tumour growth is different from that of PRL and independent of circulating PRL levels." (PMID 6788061, 1981). "Progesterone (P) (3 mg/day) alone, although without effect on PRL levels, maintained static tumour growth (i.e. it had a slight stimulatory effect) irrespective of the duration of treatment." (PMID 6788061, 1981). "The increase in plasma PRL levels above the basal values in the Ax + Ox controls following injections of combined P + Pz (0.1 mg/100 g/day) was sufficient to sustain static tumour growth, but not to reactivate growth." (PMID 6788061, 1981).
tumor (continued). "Administration of prolactin or bromocriptine to mice bearing tumours that grew independently of progesterone + oestrone treatment had no influence on tumour growth." (PMID 577471, 1977). "Before conception, magnetic resonance imaging (MRI) of the pituitary showed postoperative changes from transsphenoidal hypophysectomy and expanded partial sella, with no clear tumor, and the prolactin level was 228 ng/mL (non-pregnant normal reference range: 3-30 ng/mL)." (PMID 41769506, 2026). "Distribution of tumor type (Nonfunctioning vs. PRL) in treatment and observation groups by sex." (PMID 41480366, 2025). "We postulate that pituitary height might serve as a dynamic marker of prolactin secretion activity even in the absence of a tumor." (PMID 40966237, 2025). "In relation to the pathological subtypes of GH&PRL-PAs according to the WHO 2022 classification (n = 67), most of them were classified as mammosomatotroph (n = 50), followed by somatotroph (n = 8), lactotroph (n = 2) and mature or immature plurihormonal PIT1-lineage tumor (n = 7)." (PMID 40590355, 2025). "Consequently, both the delayed and non-delayed diagnosis groups exhibited a high proportion of prolactin reduction after tumor resolution." (PMID 38957439, 2024). "Moreover, the utilization of prolactin (PRL) hormone, a key component in mammary differentiation pathways, has been shown to suppress this oncogenic pathway, shedding light on the significant role of differentiation pathways in tumor suppression." (PMID 38473804, 2024). "However, some studies indicate that EVE combined with cabergoline (CAB) showed only additive effects in inhibiting PRL secretion, without significant synergistic effects on tumor cell proliferation." (PMID 39736867, 2024). "The tumor was completely resected, and the PRL normalized without the need for adjuvant treatment." (PMID 38516477, 2024). "Several researchers have also proposed that the secretory capacity of prolactin is related to the number of intracellular secretory granules, which may not be correlated with tumor volume." (PMID 38572480, 2024). "Progressive dose reduction and withdrawal of dopamine agonists may be considered after 2 years of treatment in asymptomatic women with normal prolactin levels and no residual tumor or with important tumor reduction on MRI." (PMID 38578473, 2024). "Besides, estradiol could stimulate PRL transcription by enhancing AP-1 and ERE activity in BC, thereby amplifying the pro-tumor potential of autocrine or paracrine PRL within the tumor microenvironment." (PMID 38898487, 2024). "Although the precise role of PRL-mediated PRL receptor (PRLR) signaling is still controversial in breast cancer cells, PRLR activation seems to be important in tumor initiation, whereas its inhibition may mitigate aggressiveness and/or dissemination of stablished tumors." (PMID 37208719, 2023). "Therefore, PRL secretion and lactotroph proliferation pathways are intimately related, which explains in part why, in general (but not invariably), PRL secretion and tumor volume run in parallel in lactotroph PitNETs, as occurs for DA response." (PMID 37762304, 2023). "The presence of amyloid deposition should also be noted in this type of PRL-producing tumor, as dopamine agonists may not shrink the tumor." (PMID 36826759, 2023). "Tumor specimens were histologically and immunohistochemical examined: anterior pituitary hormones, ki-67 labeling index, CAM 5.2, and ER∝; ER∝ expression was correlated with basal PRL levels at diagnosis (rho = 0.60, p < 0.01) and postoperative PRL levels (rho = 0.58, p < 0.001)." (PMID 38003353, 2023). "Circulating PRL levels in EGFR and HER2 transgenic mice were increased, and inhibiting EGFR or HER2 signaling with oral lapatinib suppressed circulating PRL by 72% and attenuated tumor PRL expression by 80%, and also attenuated downstream tumor EGFR/HER2 signaling." (PMID 37446128, 2023).